PKHD1 (PKHD1 ciliary IPT domain containing fibrocystin/polyductin)
Diseases named in the same sentence as PKHD1 in open-access papers (continued):
Sharing a sentence is not in itself a finding about the gene and the disease.
PKHD1 also shares sentences with these, for which no sentence is quoted: nephronophthisis (5 papers); Bardet-Biedl syndrome (3); renal fibrosis (3); chronic kidney disease (2); cystic fibrosis (2); glioma (2); kidney failure (2); nephropathies (2); portal hypertension (2); renal failure (2); Alagille Syndrome 1 (1); Alport syndrome (1); asthma (1); auditory neuropathy (1); autosomal dominant polycystic liver disease (1); basal cell carcinoma (1); breast carcinoma (1); cholestasis (1); chronic kidney failure (1); Cockayne syndrome (1); colon (1); congenital anomalies of the kidney and urinary tract (1); congenital heart malformation (1); coronary artery disease (1); Crohn disease (1); end-stage renal disease (1); Gitelman syndrome (1); Graves disease (1); Hypertension (1); intrahepatic cholangiocarcinoma (1).
A further 25 diseases each share a sentence with PKHD1 in 1 paper.